CSF1R (colony stimulating factor 1 receptor)
Diseases named in the same sentence as CSF1R in open-access papers (continued):
Sharing a sentence is not in itself a finding about the gene and the disease.
glioma (continued). "Improved efficacy however can be obtained by combining CSF1R inhibition with radiotherapy in glioma." (PMID 34539650, 2021). "In proneural gliomas, CSF-1R inhibition initially increased the survival of mice and decreased M2-like TAMs." (PMID 33919732, 2021). "Representatively, the chemoattractant molecules responsible for the myeloid cell migration to the glioma, for example, CSF-1R, avβ3/5 integrins, and CXCR4 are being targeted in multiple trials." (PMID 34084145, 2021). "That study showed that CSF-1 is expressed by GL261 glioma cells and the receptor CSF-1R is expressed by microglia, thus defining a paracrine interaction that takes place between glioma and microglia during invasion." (PMID 34843542, 2021). "PLX3397, an inhibitor of CSF1R, blocked glioma progression, markedly suppressed tumor cell proliferation and reduced tumor grade in proneural glioma mouse model." (PMID 32000794, 2020). "Recent studies have shown that CSF‐1R blockage by inhibitors or antibodies improves the efficacy of chemotherapy in multiple solid tumours, such as glioma, cervical and mammary tumour." (PMID 33037771, 2020). "Gliomas treated with DC vaccination ± murine anti–PD-1 monoclonal antibody blockade or a colony-stimulating factor 1 receptor inhibitor (PLX3397) had prolonged survival in vivo." (PMID 32986017, 2020). "The targeting of TAMs using CSF-1R inhibition blocked the acquisition of this pro-tumorigenic phenotype and enhanced initial glioma-debulking effects of radiotherapy." (PMID 33374253, 2020). "This is in contrast to prior studies demonstrating that attenuation of MCSF signaling through CSF-1R inhibition in glioma led to AAM re-education towards a pro-inflammatory M1-like phenotype." (PMID 33069212, 2020). "Since colony stimulating factor-1 (CSF-1) secreted by glioma cells is a driver of differentiation, polarization, survival, and recruitment of TAMs, strategies aimed at targeting the CSF-1 receptor (CSF-1R) on TAMs have been extensively investigated." (PMID 33374253, 2020). "CSF-1R inhibition has been shown to increase survival by blocking proneural glioma progression and resulting in the regression of established tumors." (PMID 33374253, 2020). "As previously reported, increased expression of M2‐associated genes was detected in cultured BMDMs when exposed to glioma cell‐conditioned media and that was blocked in the presence of CSF‐1R inhibitor." (PMID 33037771, 2020). "Inhibition of CSF1R has been shown to alter the expression of activated M2 markers and to reduce intracranial growth of patient-derived glioma xenografts." (PMID 32765489, 2020). "In order to investigate the effect of PDPN+ myeloid cells on glioma development, we generated a mouse line that carries a myeloid-specific deletion of Pdpn by crossing a Pdpnflox/flox with a Csf1r-Cre transgenic line." (PMID 30972297, 2019). "Multicellular gene networks connecting macrophages and tumor cells were constructed from re-grouped drug-sensitive and drug-resistant samples of RNA-seq data in mice gliomas treated with BLZ945 (a CSF1R inhibitor)." (PMID 31097021, 2019). "CSF-1R blockade using the receptor tyrosine kinase (RTK) small drug inhibitor BLZ945 (Novartis) limits glioma progression and leads to regression of established tumors." (PMID 31611871, 2019). "Inhibition of colony-stimulating factor-1 receptor (CSF-1R) by BLZ945 was shown to block glioma progression." (PMID 30644073, 2019). "The IGF-1/IGF-1R axis was identified to underlie resistance to colony-stimulating factor-1 receptor (CSF-1R) inhibition in gliomas." (PMID 31805126, 2019). "Similar combined efficacy was also seen in glioma models combining CSF1R inhibition with multiple TKIs." (PMID 29946544, 2018). "TAMs and microglia critically depend on CSF-1R for multiple functions and blockade of CSF-1R has shown therapeutic efficacy in glioma models and patients." (PMID 30619286, 2018).
glioma (continued). "In a preclinical model, the blockage of CSF-1R signaling in glioma-bearing mice by using the anti-CSF-1R antibody Pexidartinib (PLX3397) resulted in a significantly reduced tumor infiltration of GAMs." (PMID 29389898, 2018). "Attenuated interactions between CSF-1 and CSF-1R with CSF-1R-targeting inhibitors reduce the number of TAMs in tumor sites and impair the invasion ability of glioma cells." (PMID 30619286, 2018). "Macrophages also critically depend on the multiple functions of CSF-1, which is constitutively expressed by glioma cells, facilitated by its receptor CSF-1R." (PMID 30619286, 2018). "Administration of BLZ945, a small molecule inhibitor of CSF1R, in a murine model of glioma led to regression and long term increases in survival." (PMID 29946544, 2018). "Transient inhibition of CSF-1R during fWBI prolongs survival of glioma-bearing mice and fully prevents fWBI-induced memory deficits." (PMID 30421720, 2018). "In glioma-bearing mice, the blockage of CSF-1R, using the anti-CSF-1R antibody, known as Pexidartinib (PLX3397), is observed to significantly decrease tumor infiltration of GAMs leading to a reduction of the tumor volume." (PMID 30123112, 2018). "In this review, the colony-stimulating factor 1 receptor (CSF-1R) ligand CSF-1 (M-CSF) is secreted by glioma cells and facilitates the recruitment and M2 polarization of GAMs." (PMID 29389898, 2018). "Although CSF1R inhibition is expected to be a promising strategy for glioma treatment, another study suggests the potential drug-resistance mechanisms." (PMID 30619286, 2018). "Treatment with anti-CSF-1R antibodies reprograms macrophages in a glioma mouse model to a M1-phenotype and limits tumour growth." (PMID 28210073, 2017). "In gliomas, myeloid cell depletion or CSF‐1R inhibition has been shown to exert anti‐tumor effects or accelerated tumor growth." (PMID 29038312, 2017). "In vivo imaging during glioma progression at early (2 weeks)‐ and late‐stage growth (4 weeks) confirmed the recruitment of Csf1r‐Cre reporter (mG)‐ positive macrophages concomitant with the observed blood vessel diameter increase (Movies EV2 and EV3)." (PMID 29038312, 2017). "CSF1-R inhibition showed improved survival in a preclinical model of glioma, with reprograming of the TAM into pro-inflammatory cells." (PMID 28003994, 2016). "Moreover, BLZ945-mediated CSF-1R inhibition attenuated the intracranial growth of patient-derived glioma xenografts." (PMID 40867316, 2025). "Targeting and blocking CSF1R has emerged as a promising therapeutic strategy for glioma, as it could inhibit macrophage recruitment, reprogram the immune landscape, and potentially enhance the effectiveness of other treatments, such as immunotherapy." (PMID 40881678, 2025). "CSF1R (Colony Stimulating Factor 1 Receptor) promotes the recruitment of immune-suppressive macrophages to the tumor site, contributing to the immunosuppressive microenvironment that facilitates glioma progression and resistance to therapies." (PMID 40881678, 2025). "This might indicate that the gene signature for irradiated patients does not work for non-irradiated patients and may be related to the fact that animal studies indicated limited survival advantages of CSF-1R inhibition alone in mouse glioma models." (PMID 38474320, 2024). "Indeed, in a glioma mouse study, the inhibition of CSF-1R with BLZ-945 resulted in a reduction of M2 polarization within the tumor microenvironment and decreased tumor growth rates." (PMID 38474320, 2024). "However, gliomas can acquire resistance to CSF-1R inhibition mediated by changes in the TME that lead to increased secretion of interleukin (IL)-4, a potent inducer of pro-tumor, alternatively activated TAMs, from CD8+ T cells and other cell types." (PMID 38254796, 2024). "Similarly, CSF-1R knockdown in glioma cells showed a reduced expression of EMT markers such as vimentin." (PMID 38254773, 2024).
glioma (continued). "In preclinical models, CSF-1R inhibition led to decreased tumor growth and invasion, although therapeutic efficacy varied depending on the glioma subtype, possibly depending on the heterogeneity of GAMM populations discovered through a recent single-cell RNA sequencing study." (PMID 39457693, 2024). "As it may be, CSF1R inhibitors have only shown modest improvement in the short-term survival of mice bearing PDGF-B driven gliomas." (PMID 38665919, 2024). "In the present study, the findings showed that M2 macrophage markers CD163 and CSF1R were positively correlated with STEAP3 expression in glioma, suggesting that the function of STEAP3 might be related to the regulation of macrophage M2 polarization." (PMID 37009153, 2023). "Colony Stimulating Factor-1 (CSF-1) has been shown to be especially important in mediating this interaction within glioma tumors and blockade of CSF-1/CSF-1R pathway has been very effective preventing metastatic progression in many different preclinical cancer models." (PMID 36982211, 2023). "Colony stimulating factor 1 receptor (CSF1R) inhibition could regulate M2 macrophage polarization and attenuate glioma progression." (PMID 37009153, 2023). "For instance, an inhibitor of the CSF-1 receptor (CSF-1R) could significantly reduce TAMs and block glioma progression in a mouse model." (PMID 37723178, 2023). "Combining linsitinib with CSF-1R inhibitors significantly prolongs OS in the glioma mice model." (PMID 35154476, 2022). "PERTINENT FINDINGS:18F-DPA-714 PET provided complementary information to 18F-FET PET on glioma heterogeneity, allowed the imaging of immune cell dynamics, supported the assessment of brain target engagement, and elucidated CSF-1R inhibition–induced effects in vivo." (PMID 35115369, 2022). "Furthermore, in another murine glioma model, known as 005GSC, CSF1R-inhibition resulted only in modest depletion of TAMs and reduced therapeutic efficacy of an ICI regimen in combination with oncolytic immunovirotherapy." (PMID 35267626, 2022). "CSF1R-regulated signaling is crucial for the differentiation of M2 macrophage polarization in various cancers, and blockade of CSF1R could convert macrophage polarization and inhibit glioma progression." (PMID 35281049, 2022). "Therefore, CSF-1R inhibitors are expected to modulate myeloid cells within the immune-suppressive glioma tumor microenvironment." (PMID 35203505, 2022). "Furthermore, we showed that CSF-1R inhibition significantly reduced the number of GAMMs infiltrating the glioma tissue, identified as CD68+ cells, and the inhibitory effect was detected also after brain repopulation." (PMID 35115369, 2022). "However, a short-term brain repopulation period after CSF-1R therapy is highly effective in slowing glioma progression and maintaining a reduced inflammatory response." (PMID 35115369, 2022). "Furthermore, targeting TAMs using a CSF-1R inhibitor combined with radiotherapy enhanced the survival of glioma in preclinical models." (PMID 35585567, 2022). "However, gliomas developed resistance to CSF-1R through the PI3K mediated release of insulin-like growth factor 1 (IGF-1)." (PMID 33919732, 2021). "The potential for using CSF-1R targeting drugs in combination with other therapies may hold great promise for treating glioma as well as other metastatic cancers." (PMID 34843542, 2021). "Furthermore, the ability of microglia to stimulate glioma invasion in this context is heavily dependent on CSF-1R signaling." (PMID 34843542, 2021). "used CSF-1R inhibitors to target TAMs in mouse glioma models." (PMID 34722262, 2021). "Accordingly, targeting the CSF-1/CSF-1R axis may represent a potential therapeutic approach in glioma." (PMID 34950148, 2021). "However, therapeutic efficacy of CSF1R inhibition still needs to be carefully evaluated with regard to long-term efficacy and potential resistance mechanisms as observed in glioma." (PMID 34539650, 2021).
glioma (continued). "We review the current state-of-art in the field of CSF-1R inhibition in glioma and stroke and provide an overview of the fundamentals, ongoing research, potential developments of this promising therapeutic strategy and further application toward molecular imaging." (PMID 34950148, 2021). "Here we show that expression of AREG is induced in TAMs by glioma in a CSF-1R dependent manner." (PMID 34843542, 2021). "In a murine glioma model where Csf1 expression is increased approximately 2.5-fold compared to normal brain, CSF1R inhibitors decrease expression of M2 markers including Arg1 in GAMs, suggesting that increased CSF1/CSF1R signaling can promote polarization toward a M2 phenotype in the diseased CNS." (PMID 34281564, 2021). "Thus, we investigated anti-CSF1R either alone or in combination with anti-PD1 in experimental glioma." (PMID 34063518, 2021). "An inhibitor of CSF1R (colony stimulating factor 1 receptor), which controls the production and differentiation of TAMs, did not deplete these cells but favored their polarization towards a M1 phenotype, inducing a strong halt in the progression of gliomas." (PMID 32570988, 2020). "If microglia receive a stimulus, such as ionizing radiation, to prune NGS, immediately followed by CSF1R antagonism, it is conceivable that microglia will utilize their synaptic pruning capabilities to stifle glioma progression while mitigating their long-term deleterious effects on cognition." (PMID 33187183, 2020). "CSF‐1R inhibition reduced M2 macrophage polarization and regressed established gliomas." (PMID 32969157, 2020). "CSF1R blockade on myeloid cells repolarized them and diminished their tumor-promoting activity in vivo, though this strategy failed to yield significant clinical benefits in the setting of recurrent glioma." (PMID 33187183, 2020). "TAM-targeting agents like CSF-1 receptor (CSF-1R) inhibitor have shown promise by reprogramming M2-TAMs toward an anti-tumorigenic ‘M1’ phenotype in murine glioma models, yet clinical trials on GBM patients showed poor response and patients acquired resistance by the tumor microenvironment." (PMID 32909947, 2020). "CSF-1R inhibition can block the radiotherapy-induced alternative activation in MG and BMDMs and thus the acquisition of recurrence-specific phenotypes in these cells, which support glioma proliferation and regrowth." (PMID 33374253, 2020). "Therefore, combining CSF-1R blockade with PI3K or IGF-1R inhibition prolongs overall survival in recurrent gliomas." (PMID 30619286, 2018). "However, macrophages in the tumour microenvironment became refractory to the effect of anti-CSF1R antibodies resulting in regrowth of glioma tumours." (PMID 28210073, 2017). "Interestingly, treatment with two different anti-CSF-1R antibodies resulted in a macrophage reprogramming in mouse models of glioma and pancreatic cancer." (PMID 28210073, 2017). "Depletion of macrophages reduced tumor growth also in some glioma models, and interestingly, small molecule inhibition of CSF‐1R was found to dramatically block tumor growth and progression by downregulating markers of M2‐like polarization of TAMs in a proneural model of glioblastoma." (PMID 29127101, 2017). "While CSF-1R inhibition appears promising for treatment of glioma, it remains determined whether abrogation of M2 phenotype with no increase in M1 function of TAM is sufficient to drive tumor rejection in patients with GBM." (PMID 24202450, 2013). "CSF-1R–mediated modulation of GAMMs may be of high interest as therapy or cotherapy against glioma." (PMID 35115369, 2022). "Subsequently, we further evaluated the representative glioma‐associated microglia/macrophage (GAM)‐related genes expression level between high‐ and low‐risk group, higher expression level of IBA1, TMEM119, CD68, CSF1R, and TGFB1 was found in the high‐risk group." (PMID 35985661, 2022).
glioma (continued). "CSF-1R–targeting intervention and determination of the ideal treatment window for CSF-1R inhibitors may define a promising complementary therapy strategy in glioma." (PMID 35115369, 2022). "However, a colony-stimulating factor-1 receptor (CSF-1R) inhibitor aimed at obstructing accumulation of Mφs that did not alter the infiltration number of TAMs suppressed M2 function and improved prognosis in a murine glioma model." (PMID 32707672, 2020). "Thus, blocking CSF-1 or IL-34 signaling by inhibition of the common receptor CSF-1R could be an innovative treatment strategy, as shown in the glioma model." (PMID 26098772, 2015). "To determine the function of CSF-1R signaling in TAMs in GBM, we utilized human glioma scRNA-seq data." (PMID 41365876, 2025). "Instead, glioma-secreted factors such as granulocyte–macrophage colony-stimulating factor (GM-CSF) and interferon-gamma (IFN-γ) sustained TAM viability despite CSF-1R blockade." (PMID 40867316, 2025). "One can potentially lower the expressions of these DEGs using CSF-1R inhibition (e.g., using the antibody BLZ-945) among RT-treated glioma patients to achieve survival advantages, as shown in the mouse studies." (PMID 38474320, 2024). "This highlights the instrumental role of glioma-derived CSF1 and IL-34 in the differentiation of M-MDSCs, as blocking the CSF1R axis prevents expansion of the M-MDSC population in whole bone marrow." (PMID 39272914, 2024). "CSF1 has been shown to be produced directly by glioma cells and works by binding to the CSF1 receptor (CSF1R) to regulate monocyte and microglial migration and promote TAM polarization towards the M2 phenotype." (PMID 38893093, 2024). "However, combining CSF-1R inhibition with RT may significantly enhance RT-induced antitumor immunity, potentially overcoming RT resistance and resulting in long-term improvement in survival outcomes in murine gliomas." (PMID 38474320, 2024). "Recently, preclinical mechanistic studies suggested that the treatment via combining CSF-1R inhibition (e.g., via BLZ-945) with RT can enhance RT-induced antitumor immunity and lead to long-term improvement in outcomes in murine gliomas." (PMID 38474320, 2024). "The CSF-1R specific antagonist “JnJ”, is able to partially inhibit the induction of CCR1 mRNA by GL261 glioma conditioned media." (PMID 36982211, 2023). "We wanted to assess if there is any crosstalk between the CSF-1R and CCR1 pathways in glioma-stimulated microglia." (PMID 36982211, 2023). "Recently we demonstrated that CSF-1R mediates invasion in part, via upregulation of the gene Amphiregulin/AREG that presumably acts in a paracrine fashion to induce invasion of glioma cells." (PMID 36982211, 2023). "Using the GL261 model cell line, we showed in-vitro and in-vivo that blockade of TAMs using Pexidartinib/PLX3397, a blood brain barrier penetrant colony stimulating factor 1 receptor (CSF-1R) inhibitor, strongly suppresses TAM mediated glioma invasion." (PMID 36982211, 2023). "Here, we performed a multimodal, dual-tracer imaging study in a syngeneic mouse model of glioma applying 18F-FET and 18F-DPA-714 PET using a CSF-1R inhibitor to investigate the interplay between glioma progression and related immune cell dynamics." (PMID 35115369, 2022). "Administration of anti-CSF-1R and anti-PD1 to treat glioma in a mouse model indicated prolonged survival." (PMID 36013403, 2022). "Our in vitro glioma IHC analysis also confirmed the riskscore positively correlated with IBA1, TMEM119, CD68, CSF1R, and TGFB1 protein expression." (PMID 35985661, 2022). "By analyzing the glioma data in the TCGA database, the expression level of SPI1 displayed a significant positive correlation with target genes (CX3CR1: r = 0.53; CSF1R: r = 0.876; IRF8: r = 0.678)." (PMID 34434898, 2021). "While CSF-1R inhibition reduces the GAMM density, resistant cell populations were observed across different tumour types, including glioma." (PMID 34950148, 2021).